TNF (tumor necrosis factor)
Diseases named in the same sentence as TNF in open-access papers (continued):
Sharing a sentence is not in itself a finding about the gene and the disease.
atherosclerosis (continued). "Significant modules showed functions including Osteoclast differentiation, Amphetamine addiction, IL-17 signalling pathway, TNF signalling pathway, Fluid shear stress and atherosclerosis, Kaposi’s sarcoma-associated herpes virus infection and cAMP signalling pathway." (PMID 32546690, 2020). "Gustafson and colleagues reported that, among the fat storage compartments in the body, VAT was found to be an important source of pro-inflammatory adipokines such as TNF-α and IL-6, and it was associated with an increased risk for atherosclerosis, more so than subcutaneous fat." (PMID 32370212, 2020). "Longer-term studies would be needed to address whether the fall in TL1A associated with TNF therapy in RA predicts delay in progression of erosions, or development of atherosclerosis, which has also been associated with higher serum levels of TL1A." (PMID 32381123, 2020). "Furthermore, it was shown that TNFα, IL-6 and IL-12 were increased in G2A-deficient macrophages in atherosclerosis." (PMID 32708184, 2020). "Tumour necrosis factor (TNF) inhibitors are used in the treatment of certain autoimmune diseases but given the role of TNF in tumour biology and atherosclerosis, such therapies may influence the risk of cancer and cardiovascular disease." (PMID 32805626, 2020). "Increased TNF-α concentrations can cause inflammatory responses such as neutrophil recruitment, tissue destruction, neovascularization, oxidative stress, systemic inflammation, autonomic nervous system dysfunction, atherosclerosis, and aging." (PMID 32545460, 2020). "In addition to IL-1β, IL-6, and TNF-α, other circulating peptides and cytokines are linked to atherosclerosis and cardiovascular disease." (PMID 32485823, 2020). "Next, the cells were treated with TNF-α, another known risk marker for atherosclerosis." (PMID 32974343, 2020). "TNFα-deficient ApoE−/− mice had decreased plaque size compared with TNFα-sufficient ApoE−/− animals, demonstrating the deleterious role of this cytokine during atherosclerosis development." (PMID 33374145, 2020). "TNF-α was originally identified as a circulating factor which can cause necrosis of tumors and was also later found crucially involved in the pathogenesis and progression of atherosclerosis." (PMID 31534437, 2019). "However, most of the mechanistic studies exploring these associations have been performed with atherosclerosis, where TNFα promotes cholesterol accumulation in monocytes/macrophages, and atherogenesis." (PMID 30161232, 2018). "Furthermore, overexpression of miR-155 reduces chronic inflammation and provides protection against atherosclerosis-associated foam cell formation by targeting calcium-regulated heat stable protein 1, which in turn diminishes the stability of TNF-α mRNA." (PMID 29988529, 2018). "IL-6 and TNFα are produced chiefly by activated macrophages, and they are known to influence lipid metabolism and regulate the synthesis of other acute phase proteins which are established risk factors for atherosclerosis." (PMID 29801502, 2018). "TNFα is implicated in several human diseases, including atherosclerosis and cardiovascular disease." (PMID 30029641, 2018). "Moreover, TNF-α induces endothelial dysfunction and liver synthesis of clotting factors, thus predisposing individuals to atherosclerosis and atherothrombosis." (PMID 27964760, 2016). "Control of inflammation through blockade of TNF and, in turn, atherosclerosis may lead to a reduction in the risk of ischemic stroke." (PMID 26749043, 2016). "Moreover, it is associated with increased proinflammatory cytokines (IL-6, TNF-a) that contribute to atherosclerosis and CVD in high-fat composition population." (PMID 26893933, 2015). "TNF-α deficiency also reduced atherosclerosis in apolipoprotein E knockout mice." (PMID 25894557, 2015). "Additionally, in atherosclerosis, which is an age-associated pro-inflammatory condition, foam macrophages are known to produce higher amounts of TNF-α and IL-6." (PMID 26509710, 2015).
atherosclerosis (continued). "One of the key regulators of inflammation, downstream of TLRs, is NFκB, which has long been regarded as a pro-atherogenic factor, mainly because of its regulation of many pro-inflammatory genes (TNFα, IL-1, and IL-12) linked to atherosclerosis through different receptors in the macrophages." (PMID 25032960, 2014). "TNF-α, IL-1α and IL-12 are known as pathogenic factors during the development of atherosclerosis." (PMID 24708830, 2014). "Further overproduction of proinflammatory cytokines such as IL-6 or TNF-α could be a marker of chronic inflammation leading to provoked and accelerated atherosclerosis, with a higher risk of CV events and mortality." (PMID 25347067, 2014). "In fact, HIV leads to chronic immune activation and a prothrombotic state, which also features increases in interleukin-1, interleukin-6, and tumor necrosis factor-α which have been implicated in the pathogenesis of atherosclerosis, progression to AIDS, and mortality in HIV-infected persons." (PMID 23394360, 2013). "Besides, the disruption of TNF-α gene diminishes the development of atherosclerosis in ApoE-deficient mice." (PMID 23895132, 2013). "Also, atherosclerosis is reduced in ApoE−/− mice deficient in TNFα and IFNγ potentiates atherosclerosis in these mice." (PMID 23560095, 2013). "TNF-α mediated inflammation in vascular smooth muscle cells, as well as macrophages and endothelial cells, is believed to be a major mechanism underlying the pathophysiology of atherosclerosis." (PMID 24098382, 2013). "A variety of variables (CRP, complement C3, IL-6 and TNF-α) implicated in the regulation of the inflammatory process and, in turn, in the pathophysiology of arthritides, are relevant in the etiology and the development of atherosclerosis." (PMID 23036698, 2012). "Hence, enhanced PON1 antioxidant capacity was found to be associated with reduced TNF-alpha levels, probably protective against atherosclerosis." (PMID 21569287, 2011). "Plasma TNF-α concentrations predict vascular damage, since they are associated with early atherosclerosis in middle-aged healthy men; furthermore, elevations of TNF-α in the stable phase after myocardial infarction were associated with an increased risk of recurrent coronary events." (PMID 20652043, 2010). "Consequently, atherosclerotic lesions were smaller and characterized by strongly reduced expression of inflammatory cytokines, such as TNF and IL-6 and also reduced expression of atherosclerosis associated chemokines, such as MCP-1 and RANTES." (PMID 19582157, 2009). "TNF-α signaling in these three cell types, aortic smooth muscle, endothelial, and macrophage, is believed to be a major contributing factor to the inflammatory processes underlying the development and progression of atherosclerosis." (PMID 20029624, 2009). "Additionally, the TNF and NF‐κB signaling pathways highlight the contribution of systemic inflammation originating from the liver (“hepatic‐inflammatory axis”) to endothelial dysfunction, a hallmark of atherosclerosis and CHD." (PMID 41551909, 2026). "In this regard, TNF-alpha eventually comes out as a pivotal biomarker of inflammation that is strongly associated with atherosclerosis formation and subsequent ASCVD development." (PMID 40759997, 2025). "Furthermore, modulating IL-4, TNF-α, and IL-1β expression suggests an immunomodulatory effect that could reduce atherosclerosis risk." (PMID 40630842, 2025). "Therefore, these alterations could lead to production of specific inflammatory cytokines, such as IL-1, IL-6, and TNF-a, and enhancement of inflammation, all known risk factors for the development of atherosclerosis and CAD." (PMID 40566026, 2025). "Furthermore, this inflammation is a key pathological link between immune dysfunction and the vastly elevated cardiovascular risk in ESRD, as pro-inflammatory cytokines like IL-6 and TNF-α promote endothelial dysfunction, atherosclerosis, and vascular calcification." (PMID 41010736, 2025).
atherosclerosis (continued). "Furthermore, the pro-inflammatory cytokines IL-8 and TNF-α are central mediators in the chronic inflammatory state that drives atherosclerosis, protein-energy wasting, and is strongly associated with adverse cardiovascular outcomes and mortality in hemodialysis patients." (PMID 41414686, 2025). "In addition, abatacept has been compared with TNF-α inhibitors and may improve insulin sensitivity and lipid profiles in RA patients at high risk of accelerated atherosclerosis, similar to diabetic or elderly patients." (PMID 38929699, 2024). "Pro-inflammatory cytokines such as IL-1β, IL-6 and TNF-α and anti-inflammatory cytokines such as IL-4 and IL-10 provide further insights into the mediators of cellular and systemic responses and have been linked to causal pathways related to atherosclerosis and thrombosis." (PMID 39767790, 2024). "The strong correlations found with the compound scores, particularly compound score 2, that comprised both TNF-alpha and hsCRP values, suggest that integrating multiple maternal risk factors provides a more effective predictive tool for identifying fetuses at risk of developing atherosclerosis." (PMID 39518658, 2024). "However, the chronic inflammation present in atherosclerosis continues to cause havoc as the pro-inflammatory cytokines released (such as TNF-α and IL-1) recruit more macrophages and stimulate the production of growth factors responsible for vSMC production at the inflamed site." (PMID 36865918, 2023). "In addition, endothelial injury caused by HFD-induced atherosclerosis may enhance the production of ROS in vascular endothelial cells, thereby promoting the secretion of the inflammatory cytokines TNF-α and IL-1β." (PMID 37764856, 2023). "In addition to the effects on lesion size, lipid profile, and oxidation, curcumin also affects inflammation, another hallmark of atherosclerosis, by reducing systemic levels of inflammatory cytokines such as IL-6, Tumor necrosis factor-alpha (TNFα), and C-reactive protein (CRP)." (PMID 35159155, 2022). "Not surprisingly, the major proinflammatory cytokines involved in RA pathogenesis, TNF-α and IL-1, have been shown to upregulate heparanase expression in endothelial cells, which may be a potential cause of an increased risk of atherosclerosis associated with this arthropathy." (PMID 35887981, 2022). "However, dysregulation of TNF leads to chronic inflammation by activating the nuclear factor-kappa B (NF-κB) signaling pathway, and is associated with several human inflammatory pathologies and diseases, such as cancer, atherosclerosis, and type-2 diabetes." (PMID 34067297, 2021). "Thus, commonly used CHPs might suppress the production of IL-6 and TNF-α, the same proinflammatory cytokines active in the process of atherosclerosis, to reduce the risk of CAD." (PMID 32228568, 2020). "Thus, increased levels of TNF-α were associated with greater chance of atherosclerosis." (PMID 31664319, 2020). "Here, the inflammatory molecules in our panel that showed the most significance in PD, and particularly IL-1α, IL-1β, IL-17A, and TNF-α are all known to be dysregulated in cardiovascular disease and their presence in circulation might be linked to atherosclerosis." (PMID 31507404, 2019). "Furthermore, aside from inducing IFN-γ, IL-18 can also induce expression of TNF-α and synthesis of IL-10, cytokines that can inhibit the inflammatory process, leading to the instability of atherosclerosis plaques and formation of thromboses, a main risk factor for stroke." (PMID 31525735, 2019). "In addition, macrophages with low LRP1 levels may contribute to the exacerbation of the inflammatory process, as it has been previously shown that macrophage LRP1 deficiency contributes to increased MMP‐9, MCP‐1 and TNF‐α secretion in atherosclerosis." (PMID 28378397, 2017).
atherosclerosis (continued). "Also, although inflammatory cytokines like TNF could “replace” LPS as signal 1, endotoxins are also relevant for atherogenesis, and endotoxemia is shown to be a strong risk factor for atherosclerosis." (PMID 29176764, 2017). "In addition, IL-6 and TNF-α can play a pivotal role in inflammation-associated disturbances in glucose and insulin metabolism, lipid homeostasis, endothelial dysfunction, and accelerated atherosclerosis." (PMID 27616738, 2016). "As the miR-17-92 cluster is significantly downregulated in patients with CAD, and TNF-α is important with respect to the development of atherosclerosis, we hypothesized that the miR-17-92 cluster is closely associated with TNF-α-induced apoptosis in endothelial cells." (PMID 26459935, 2015). "Moreover, both TNF-α and IL-6 are involved in the inflammatory response occurring in the vascular endothelial cells and promote the initiation and evolution of atherosclerosis by causing endothelial cells to express adhesion molecules and induced endothelial dysfunctions." (PMID 23970974, 2013). "In addition, in light of numerous clinical data suggesting a causative linkage between inflammation and enhanced atherosclerosis, we further hypothesized that tumor necrosis factor (TNF)-α might be involved in leptin induction within the carotid plaque." (PMID 23316287, 2012). "Also in genetically CCR5 deficient mice with diet induced atherosclerosis, reduced lesion size, increased IL-10 and decreased TNF-α production by CD4+ and CD8+ T cells, and reduced macrophage accumulation in plaques and lowered circulating IL-6 levels was seen." (PMID 22348061, 2012). "KEGG enrichment analysis indicated that the overlapping targets are primarily involved in inflammatory and metabolic pathways, including the AGE-RAGE signaling pathway, the lipid and atherosclerosis pathway, and the TNF signaling pathway." (PMID 40798949, 2026). "Inflammatory pathways involving tumor necrosis factor, interleukin-17, and interleukin-6 appear to promote endothelial activation, oxidative stress, lipid dysfunction, vascular remodeling, and atherosclerosis." (PMID 42232977, 2026). "Research into other inflammatory mediators, such as IL-6, TNF-α, and monocyte chemoattractant protein-1, with potential therapeutic options for preventing the rapid progression of atherosclerosis in NCVs is ongoing." (PMID 41517773, 2026). "Mercury also promotes vascular smooth muscle proliferation and endothelial inflammation via proinflammatory cytokines such as interleukin-6 and TNF-α, contributing to atherosclerosis, systemic hypertension, and cerebrovascular disease." (PMID 41323174, 2026). "The demonstrated efficacy of TNF inhibitors for the treatmentof other inflammatory diseases provides a good basis for using existingdevelopments for testing directly on atherosclerosis models." (PMID 40160593, 2025). "They inhibit the expression of pro-inflammatory cytokines such as IL-6, TNF-α, and C-reactive protein (CRP), which are directly implicated in the pathogenesis of atherosclerosis." (PMID 40807170, 2025). "In atherosclerosis, miR-146a exhibits anti-inflammatory properties by inhibiting the NF-κB pathway and regulating cytokine expression, including IL-6, IL-8, IL-17 and TNFα." (PMID 40332077, 2025). "Through comprehensive network pharmacology and multi-omics analysis, this study predicts that the core components of H. cordata play a role in treating NSCLC by regulating lipid and atherosclerosis, as well as the TNF signaling pathway." (PMID 39440769, 2025). "GO and KEGG pathway enrichment analysis highlighted potential signaling pathways, such as AGE-RAGE, PPAR, insulin resistance, TNF, and lipid and atherosclerosis pathways." (PMID 41304686, 2025). "Several studies have demonstrated that hyperinsulinemia can activate pro-inflammatory pathways, leading to elevated levels of cytokines such as IL-6 and TNF-α, which further impair vascular function and promote atherosclerosis." (PMID 40265186, 2025).
atherosclerosis (continued). "On the other hand, hypomethylation of inflammatory genes (e.g., TNF-α and IL-6) can drive chronic inflammation, promoting atherosclerosis and plaque instability." (PMID 40416162, 2025). "Extensive research has shed light on the TNF‐α signaling pathway and its potential implication in atherosclerosis progression." (PMID 40161001, 2025). "KEGG analysis revealed enrichment in pathways such as “lipid and atherosclerosis”, “mTOR signaling pathway”, “ferroptosis”, “TNF signaling pathway”, and “Th17 cell differentiation”." (PMID 41515900, 2025). "Migraine sufferers are more prone to developing arterial atherosclerosis, which contains eleven targets including Akt1, TNF, IL-6, etc.." (PMID 41009787, 2025). "IL-17 stimulates macrophages to release pro-inflammatory cytokines, such as TNF-α and IL-6, which are involved in the formation and progression of atherosclerosis." (PMID 40276600, 2025). "The JAK2/STAT3 signaling pathway is a classical inflammatory signaling pathway that regulates macrophage polarity toward the M1 phenotype and modulates the secretion of inflammatory factors (e.g., TNF-α), which exacerbates the course of atherosclerosis." (PMID 40647133, 2025). "Highlighting TNF-α’s relationship with NF-κB, an essential regulator of inflammation, is crucial to understanding the processes by which it affects atherosclerosis." (PMID 40006011, 2025). "These mutated cells, particularly in older adults, produce increased levels of inflammatory cytokines, including IL- 6 and TNF-α, which are known to exacerbate atherosclerosis." (PMID 40407975, 2025). "Of them, we noticed that several crucial pathways involving MI were significantly enriched, such as lipid and atherosclerosis and the TNF signaling pathway." (PMID 40365322, 2025). "PPAR-γ agonists suppress pro-inflammatory cytokines (e.g., TNF-α, IL-6) and reduce vascular inflammation, which is a key driver of atherosclerosis." (PMID 40568287, 2025). "Visceral adiposity secretes the pro-inflammatory cytokines interleukin-6 (IL-6) and tumor necrosis factor-α (TNF-α), reducing endothelial nitric oxide and upregulating adhesion molecules that initiate atherosclerosis." (PMID 40727914, 2025). "Among these differential genes, upregulated genes were mainly enriched in pathways such as the IL-17 signaling pathway, legionellosis, lipid and atherosclerosis, TNF signaling pathway, and antigen processing and presentation." (PMID 40616092, 2025). "Lipid markers, including Lp-PLA2 and oxylipins, elucidate lipid metabolism’s contribution to atherosclerosis, while inflammatory biomarkers like TNFα, IL-6, GDF-15, and PTX3 highlight the role of chronic inflammation in CVD progression." (PMID 40244022, 2025). "According to KEGG analysis, the pathways primarily involved the AGE-RAGE signaling pathway, fluid shear stress and atherosclerosis, lipid and atherosclerosis, TNF signaling pathway, HIF-1 signaling pathway, MAPK signaling pathway, and IL-17 signaling pathway." (PMID 40237055, 2025). "Cytokines, such as IL-6 and TNF-α, facilitate atherosclerosis, and vascular damage activates cells like osteoblasts and osteoclasts, further accelerating atherosclerosis as reported in some studies." (PMID 39697523, 2025). "Anti-TNF-α therapies have shown promise in reducing CV morbidity and mortality in AS patients, with evidence suggesting their role in mitigating subclinical atherosclerosis through anti-inflammatory mechanisms." (PMID 39859250, 2025). "An in vivo study revealed that a deficiency in another major inflammatory cytokine, tumor necrosis factor (TNF)-α, reduced the onset of atherosclerosis." (PMID 41424804, 2025). "In the aEC_cluster, we identified a significant upregulation of pathways associated with fluid shear stress and atherosclerosis, growth hormone synthesis, inflammatory mediator regulation of TRP channels, and TNF signaling." (PMID 40963808, 2025).